TLR3 (toll like receptor 3)
Diseases named in the same sentence as TLR3 in open-access papers (continued):
Sharing a sentence is not in itself a finding about the gene and the disease.
tumor (continued). "Converting tumour‐supporting macrophages to tumour suppressors that produce inflammatory cytokines and promote M1 polarization is another suggested mechanism that has been attributed to the anti‐tumour activity of poly I:C‐activated TLR3." (PMID 33336901, 2021). "Activation of lung alveolar epithelial TLR3 by tumor exosomal RNAs can recruit neutrophils, which can promote the formation of the lung premetastatic niche." (PMID 33986756, 2021). "In this work, we have developed a semi-mechanistic model for the antitumor effects of combination treatments based on three immune-modulators—a tumor-antigen, a toll-like receptor-3, and an αPD1—in a cold tumor." (PMID 34680196, 2021). "This was supported by administration of TLR3 agonist in a murine tumor, leading to shift in macrophage phenotype from M2 to M1 and regression of tumor growth." (PMID 34771568, 2021). "TLR3/7/9−/− mice showed a delay in tumor regression and only a partial tumor volume reduction compared to WT mice." (PMID 34341449, 2021). "As TLR3 on DCs plays an important role in anti-tumor immunity, it is the key factor for the cross-activation of antigen-specific CD8+ T cells." (PMID 33732237, 2021). "TIMER analysis showed that TLR3 was negatively correlated with the tumor purity of LUAD and positively with immune cell infiltration to some extent." (PMID 34094905, 2021). "In AT-3 tumor-bearing mice, we found that intratumoral administration of Flt3L more effectively controlled tumor growth than systemic injection in combination with RT and in situ TLR3/CD40 stimulation." (PMID 33110069, 2020). "To this end, we irradiated primary or distant tumor in combination with in situ administration of Flt3L and TLR3/CD40 agonists to the primary tumor in mice bearing bilateral AT-3 tumors." (PMID 33110069, 2020). "The capability of TLR3 agonists to boost the immune response in tumor microenvironment has been widely investigated in preclinical models." (PMID 32093313, 2020). "Here, our evidences indicate the promotion of apoptosis cascade and the engagement of the immune system as the two main outcomes of TLR3 activation on tumor cells." (PMID 32093313, 2020). "Studies also showed that skin injury increases IL-36γ expression in epidermal keratinocytes, and that TLR3 is required for the induction of IL-36γ18,54." (PMID 32901055, 2020). "Agonists for, e.g. TLR3 have been shown to induce apoptosis of tumor cells, and recently, a TLR2 agonist that generates macrophages with strong anti-tumor potential has been discovered." (PMID 32244723, 2020). "In recent years, multiple studies have demonstrated that TLR3 expression and activation play a role in tumor progression." (PMID 33147700, 2020). "Most studies were focused on the beneficial role of TLR3 activation in tumor cells, which leads to the production of cytotoxic cytokines and interferons and promotes caspase-dependent apoptosis." (PMID 33147700, 2020). "On the other hand, TLR3 activation can induce apoptosis in tumor cells which has been extensively demonstrated." (PMID 33147700, 2020). "This study being led by Brody and colleagues has shown that this vaccine strategy induces successful antigen cross-presentation in TLR3+ DCs of tumor microenvironment and subsequent tumor regression in a clinical trial of indolent non-Hodgkin’s lymphoma." (PMID 32937885, 2020). "This study found that doxorubicin stimulates the rapid production of type I IFNs by tumor cells, which is dependent on the endosomal pattern recognition receptor TLR3." (PMID 32326356, 2020). "In this perspective, we focus on the mechanisms through which TLR3 can either lead to tumor regression or promote carcinogenesis as well as on the potential of TLR-based therapies in resistant cancer." (PMID 33147700, 2020). "In turn, low TLR3 expression was significantly correlated with tumor size (P = 0.007) and venous invasion (P = 0.016)." (PMID 33173017, 2020).
tumor (continued). "The prognostic value of Toll-like receptor 3 (TLR3) is debated in cancer, differing between tumor types, methods, and cell types." (PMID 32093313, 2020). "The anti-tumour effects of the TLR3 agonists were also abolished in IFNAR1 knockout mice, highlighting a key role for type I IFN signalling." (PMID 33352882, 2020). "In ESCC, TLR-3 overexpression was significantly correlated with worse clinical parameters, while higher levels of TLR-9 were positively associated with advanced tumour grade, lymph node and distant metastases." (PMID 33008143, 2020). "Another study showed that the administration of ARNAX, a TLR3-specific adjuvant, with a tumor-specific antigen promoted tumor regression." (PMID 33633744, 2020). "T-cell activation by a DNA vaccine encoding HPV E7 and combined with TLR4 ligands augmented antitumor responses in a mouse tumor model, and the combination of DNA vaccine with TLR3 or 7 ligands also showed increased antitumor responses." (PMID 33008010, 2020). "Toll-like receptor 3 (TLR3) ligand which activates TLR3 signaling induces both cancer cell death and activates anti-tumor immunity." (PMID 33036630, 2020). "The majority of clinical studies establish TLR3 as a tumor suppressor using synthetic ligand polyinosinic:polycytidylic acid [poly(I:C)] or poly-ICLC for adjuvant therapy or targeted therapy." (PMID 33072559, 2020). "In the present review, the clinical studies revealed differential expressions of the TLR family in various HNSCC tumours, of which TLR-3, 4, 5, 7 and 9 had certain prognostic values in their respective tumours." (PMID 33008143, 2020). "In the present review, we summarize the current knowledge of the mechanisms through which TLR3 can either lead to tumor regression or promote carcinogenesis as well as the potential of TLR-based therapies in resistant cancer." (PMID 33147700, 2020). "These molecules are sensed by endosomal TLR-3 in both viable tumor cells and tumor-infiltrating DC and activate complex signaling pathways, ultimately leading to interferon-stimulated gene (ISG) expression and type I IFN production." (PMID 32290265, 2020). "In line with previous reports, PDL1 upregulation by MAFO was dependent on IFNAR and TLR-3 signaling as it was abrogated in tumor cells where IFNAR1 was blocked by neutralizing Ab or in MCA-Tlr3-/-." (PMID 32290265, 2020). "Despite positive effects on apoptosis, a contrary role of TLR3 in tumor progression and invasiveness has also been proposed." (PMID 33147700, 2020). "In contrast to these findings, recent evidence showed a link between TLR3 and tumor progression, metastasis, and therapy resistance." (PMID 33147700, 2020). "Multiple studies have described the ability of TLR3 to induce apoptosis in different in vitro tumor models, mostly through activation of caspases." (PMID 33147700, 2020). "TLR3 has been reported as one of novel therapeutic targets that can eliminate cancer cells and activate anti-tumor immunity." (PMID 33036630, 2020). "It is known, for instance, that TLR3 activation in host immune cells present in the tumor microenvironment induces the activation of cells, such as tumor-suppressive M1 macrophages or tumor-associated CD11b+Ly6G+ neutrophils, with final tumoricidal outcome." (PMID 33147700, 2020). "For example, poly-ICLC (TLR3 agonist; vaccine adjuvant discussed vide supra) decreases tumor and peripheral MDSCs." (PMID 32937885, 2020). "Taken together, multiple studies have shown a strong ability of TLR3 to promote caspase-dependent apoptosis in cancer cells, once the receptor is activated, with beneficial outcome in in vitro and in vivo tumor reduction." (PMID 33147700, 2020). "In fact, lung epithelial TLR3 was activated by exosomal RNAs derived from the primary tumor, stimulating NF-κB, ERK, and p38 pathways to secrete chemokines." (PMID 33147700, 2020).
tumor (continued). "We and others observed the expression of TLR3 protein NSCLC specimens by immunohistochemistry, and we revealed that the expression of TLR3 on tumor cells has a favorable prognostic value in early stage human NSCLC." (PMID 32093313, 2020). "Increased TLR3 expression in human melanoma cells after pretreatment with a type I IFN results in the inhibition of proliferation with subsequent death of these tumor cells." (PMID 32012718, 2020). "Among TLRs, Toll-like receptor 3 (TLR3) is one of the promising targets that represents a potential for anti-tumor therapy." (PMID 33036630, 2020). "Summed up, studies on breast, prostate, lung, and intestinal carcinomas support the role of TLR3 activation in tumor progression via enhanced cancer stemness, metastasis, and metabolic sustainment." (PMID 33147700, 2020). "Activation of TLR3 on tumor cells can also lead to tumor killing by initiating apoptosis, as has been demonstrated with the HPV vaccines BiVax and TriVax13,14." (PMID 30992466, 2019). "The effect of DaRT combined with the TLR3 agonist poly I:C on tumor development was investigated in the immunogenic CT26 tumor model." (PMID 31637474, 2019). "In contrast, previous studies have identified TRIM56 as a tumor suppressor through activation of TLR3/TRIF signaling pathway, which was consistent with the result that TRIM56 expression was a favorable indicator of MIBC in this study." (PMID 31866765, 2019). "TLR3 has an opposite prognostic significance when expressed on tumor or immune cells in early stage NCSCL." (PMID 31582772, 2019). "Collectively, the data show that TLR3 agonist Riboxxol can be selectively delivered to xenografted tumor cells expressing the cognate surface receptor in vivo by assembled RICIA immunoconjugates." (PMID 30824859, 2019). "We have recently shown that stimulation of tumor-conditioned macrophages with poly I:C (TLR3 agonist) is superior to imiquimod (R837) for their reprogramming into cytotoxic effectors." (PMID 31878087, 2019). "Then, these data suggested that the great majority of TLR3 protein in NSCLC arise from tumor cells instead from immune cells." (PMID 31582772, 2019). "In a cohort of 194 NSCLC stage I, TLR3 immunohistochemistry expression on tumor cells predicted a favorable outcome of early stage NSCLC, whereas on the immune cells infiltrating the tumor stroma, TLR3 expression associated with a poor overall survival." (PMID 31582772, 2019). "Local treatment prior to DaRT, with the TLR3 agonist poly I:C, was sufficient to inhibit tumor growth relative to poly I:C or DaRT alone." (PMID 31637474, 2019). "TEVs carrying specific RNAs activate Toll-like receptor 3 (TLR3) in stromal cells thus promoting tumor growth and establishing a proper tumor niche by inducing neutrophil recruitment and immobilization at the tumor location." (PMID 31137912, 2019). "In this study we investigated the expression and the prognostic value of TLR3 on both tumor and immune compartments of stage I NSCLCs." (PMID 31582772, 2019). "The use of TLR3 agonists as immunotherapeutic agents has been employed in cancer therapy to induce tumor cell apoptosis in type I IFN-dependent and independent pathways." (PMID 31130960, 2019). "IHC performed on FFPE NSCLC specimens using the 40F9.6 mAb11 showed TLR3 expression in tumor cells (TLR3-t) and in immune cells infiltrating the stroma (TLR3-s) or the tumor (TLR3-i)." (PMID 31582772, 2019). "The expression of both TLR3 and PD-1 on immune cells infiltrating the tumor stroma in the same cases was strongly associated with the expression of cyclooxygenase-2 (COX-2) on tumor cells (Chi square p value < 0.0001)." (PMID 31582772, 2019). "Combining BRAF inhibition therapy with Flt3-L and the TLR-3 agonist polyinosinic:polycytidylic acid (poly-I:C), to expand and activate intra-tumoral cDC1, leads to more effective anti-tumor therapy." (PMID 30979057, 2019).
tumor (continued). "SVNPs are composed of two types of NPs: one carrying the adjuvant, a toll-like receptor 3 (TLR3) agonist (poly I:C), and the other carrying the model tumor antigen, ovalbumin (OVA) prepared by electrostatic adsorption." (PMID 31695807, 2019). "According with smoking habit, tendency towards a good prognosis was observed in smokers expressing TLR3 protein in the tumor cells (p = 0.1461; HR = 0.704; CI = 0.439–1.130)." (PMID 31582772, 2019). "Such targeted delivery of TLR3 agonists can be accomplished by implementing an antibody or specific ligand for a surface tumor antigen, which upon crosslinking is endocytosed by the tumor cell and delivers the agonist to endosomal TLR3." (PMID 30824859, 2019). "So far, there is accumulating evidence that activation of TLR3 in tumor cells and tumor stroma preferentially results in anti-tumor effects." (PMID 30824859, 2019). "This is in accordance with what previous observed in IHC analysis, since distribution of cases by expression pattern of TLR3 suggested that the great majority of TLR3 protein in NSCLC arise from tumor cells instead from immune cells." (PMID 31582772, 2019). "Yet, when considering a systemic application of natural or synthetic TLR3 agonists to treat tumor cells, the targeted delivery of TLR3 agonists appears advantageous since off-target effects are limited." (PMID 30824859, 2019). "It was described how the cancer autocrine axis of TLR3 > IFNs-I > IFNAR affects immunogenicity of anthracycline-mediated tumor cell death." (PMID 31781113, 2019). "We show that CD103+ cDC1 and, to a much lesser extent CD11b+ cDC2, are the only populations expressing TLR3 at the tumor site." (PMID 30949170, 2019). "TLR3 activation on immune cells can boost the inflammatory immune mileau towards a tumor supporting microenvironment." (PMID 31582772, 2019). "TLR3 is highly expressed by cross-presenting DC subsets, which are critical to induce anti-tumor CD8+ T cell responses." (PMID 30979057, 2019). "Evident showed that Poly (I:C) can induce the secretion of MHC class I molecules via TLR3 signaling pathway, increasing the tumor immunogenicity to overcome this resistance." (PMID 30127747, 2018). "The PRR, TLR3, was shown to participate in immune surveillance and result in tumor regression especially in lungs." (PMID 29449840, 2018). "Altogether, these results suggest that paclitaxel and Poly(I:C) act synergistically to inhibit tumor growth in immunocompromised mice via the direct and selective induction of apoptosis by TLR3 in cancer cells." (PMID 30158588, 2018). "As previously shown, therapy with a TLR3 agonist leads to DC activation and increased infiltration of Teff in the tumor, in addition to a decrease in tumor-infiltrating Tregs." (PMID 29755681, 2018). "Although, signaling through TLR-3 showed a promising effect on the regression of tumor growth, nothing has been elucidated on its influence on TAMs." (PMID 30072995, 2018). "We show that activating DCs through TLR3 agonists enhances the anti-tumor immune response to CB and increases survival in GBM." (PMID 29755681, 2018). "In this type of carcinoma, however, TLR3 was found to have elevated levels and this event was attributed to an increase of tumor aggressiveness and invasion, a similar conclusion of another study which measured TLR3 in various HNSCC cell lines." (PMID 29854832, 2018). "This suggests that TLR-3 stimulation skews the macrophages toward M1 phenotype which not only activates T cells but also prevents tumor progression." (PMID 30072995, 2018). "Mice treated with TLR3 agonist poly(I:C) and anti-PD-1 demonstrated increased DC activation and increased T cell proliferation in tumor draining lymph nodes." (PMID 29755681, 2018). "We previously reported that TLR3-specific CTL-priming adjuvant enhanced the therapeutic efficacy of PD-L1 blockade in some tumor-bearing mice models." (PMID 29593736, 2018).
tumor (continued). "Other pre-clinical studies using glioblastoma models in mice have shown that activating DCs via the TLR3 agonist (poly I:C) in the tumor-draining lymph node can enhance the anti-tumor immune response to checkpoint blockade and increase survival." (PMID 30301252, 2018). "Conversion of pro-tumor TAMs to anti-tumor macrophages (e.g., M1 macrophages) was accomplished in vitro and in an in vivo murine tumor model via stimulation of toll-like receptor-3 (TLR-3) signaling by administration of poly (I:C)." (PMID 30420856, 2018). "TLR3 was selectively up-regulated by TC1 primary tumour cells and this was corroborated by enhanced expression of genes associated with the IFNγ signaling pathway." (PMID 29440650, 2018). "In another OSCC study, TLR3 was found to be upregulated in three head and neck cell lines (mRNA and protein), as well as when it induced apoptosis of the tumor cells, and in vivo, when it interrupted tumor growth." (PMID 29854832, 2018). "The histological analysis revealed that reovirus treatment of TLR3 knocked out tumor has a different morphology than those with unmodified HCT116 cells." (PMID 28422714, 2017). "TLR3 adjuvant is now considered more successful in tumor immunotherapy compared to other TLR adjuvants." (PMID 29041928, 2017). "Further studies elucidating the mechanism of tumor evasion from CTL cytotoxicity and the development of appropriate protocols for TLR3 adjuvant therapy would prove useful in this field to allow for complete tumor regression in cancer patients." (PMID 29312355, 2017). "In a tumor-bearing mouse model, CD11b+Ly6G+ cells (i.e. myeloid-derived suppressor cells) express high tumoricidal activity in response to TLR3 agonist by production of reactive oxygen species (ROS)." (PMID 28114402, 2017). "Small nuclear RNA from tumor-derived exosomes has recently been demonstrated to activate TLR3 on lung epithelial cells." (PMID 28717003, 2017). "Histologic analysis of tumour sections, taken from WT and Tlr3/7/9−/− mice at different time points during the initial growth and the later rejection phase, confirmed tumour regression." (PMID 28300057, 2017). "A type I IFN response induced by TLR3 pathway can be involved in tumor cells death directly or indirectly." (PMID 28790362, 2017). "In this scenario, bacterial-derived dsRNA behaves like a tumor suppressor via c-Myc regulation through the TLR3 signaling pathway." (PMID 29041928, 2017). "In vivo experiments using human CRC cells derived xenografts in athymic mice further demonstrate the beneficial effects of TLR3 knock down by improving tumor response rates to reovirus." (PMID 28422714, 2017). "Upon reovirus treatment of the tumors we observed a greater degree of tumor growth inhibition in TLR3 down-regulated tumor as compared to tumors with unmodified TLR3." (PMID 28422714, 2017). "The TLR3–TICAM-1 pathway is critical for poly(I:C)-induced tumor regression via stromal macrophages in the 3LL tumor mouse model." (PMID 29312355, 2017). "High TLR3 expression in tumor cells has therefore been appreciated as a way to target these cells using poly(I:C)." (PMID 28717003, 2017). "As depicted in the study design scheme, the DC injection was followed immediately with intramuscular injection of poly(IC:LC), a toll-like receptor 3 (TLR3) ligand in order to provide a DC maturation signal and enhance expansion of tumor infiltrating T cells." (PMID 28388966, 2017). "The TLR3 agonist poly (I:C) activated TLR3 pathway and inhibited tumor cells proliferation through caspase-dependent apoptosis." (PMID 28790362, 2017). "RNA adjuvant therapy mimicking dsRNA by Poly(I:C) modulated tumor infiltrating myeloid cells via TLR3/TICAM-1 pathway from tumor-supportive to tumor-suppressive." (PMID 27886105, 2016). "The consistent expression of TLR3 by malignant cells raises the question of its potential role in oncogenesis and tumor progression." (PMID 27791989, 2016).